Y_RNA (Y RNA )
Gene: Miscellaneous RNA gene on chromosome 4 (78,632,273 to 78,632,385, reverse strand). Ensembl gene ENSG00000200998.
Homologues: Orthologues: chimpanzee Y_RNA (100% identical). Paralogues in human: RNY1 (89% identical), Y_RNA (89% identical), Y_RNA (88% identical), RNY1P7 (87% identical), Y_RNA (87% identical), RNY1P11 (86% identical), RNY1P8 (86% identical), Y_RNA (86% identical), Y_RNA (85% identical), Y_RNA (84% identical), Y_RNA (83% identical), Y_RNA (82% identical), and 97 more.